HMGB1 (high mobility group box 1)
Diseases named in the same sentence as HMGB1 in open-access papers (continued):
Sharing a sentence is not in itself a finding about the gene and the disease.
pneumonia (43 papers, 2011 to 2025). An acute, acute and chronic, or chronic inflammation focally or diffusely affecting the lung parenchyma, caused by an infection in one or both of the lungs (by bacteria, viruses, fungi, or mycoplasma.). "Similar to cancer patients, greater amounts of HMGB1 are released into the serum of patients with influenza A virus infection, which is associated with severe pneumonia." (PMID 36139393, 2022). "Influenza-infected patients express elevated circulating HMGB1 concentrations that are associated with the development of severe pneumonia." (PMID 32380958, 2020). "Recent studies in our lab indicated that hyperoxia-suppressed bacterial clearance in PA pneumonia is associated with a substantial accumulation of extracellular HMGB1 in the airways." (PMID 33126860, 2020). "In pneumonia and ARDS, HMGB1 is emerging as a biomarker of mortality risk, whereas in child pneumonia HMGB1 permits to discriminate between coinfection (bacterial and viral) vs. single infection." (PMID 32760352, 2020). "Recently reported data support the view that treatment with a neutralizing anti-HMGB1 antibody ameliorated pulmonary damage in a murine model of pneumonia caused by a pathogenic strain of Staphylococcus aureus." (PMID 25029244, 2014). "HMGB1 has been shown to impair bacterial clearance during pneumonia caused by Pseudomonas (P.)aeruginosa." (PMID 24342460, 2013). "The data obtained by Achouiti and colleagues suggest that HMGB1 might be a viable drug target in patients with pneumonia caused by S. aureus, but the study conducted by Achouiti and colleagues has some limitations." (PMID 25029244, 2014). "In response to infectious agents including influenza and pneumonia, inflammatory ligands including Acute Glycation Endproducts (AGEs), S100 calgranulins, and high mobility group box 1 (HMGB1) bind RAGE." (PMID 36670409, 2023). "The data are supported by the fact that HMGB1 is associated with RSV-induced bronchiolitis, neonatal ARDS, pediatric asthma, and pneumonia." (PMID 35633962, 2022). "Several diagnostic biomarkers have been connected to pneumonia, among which are C-reactive protein (CRP), Procalcitonin (PCT), a Soluble triggering receptor expressed on myeloid cells-1 (STREM-1), CD163, and High Mobility Group Box-1(HMGB-1)." (PMID 34663864, 2021). "A heparin derivative, 2-O, 3-O desulfated heparin (ODSH), has been shown to inhibit HMGB1 release from a macrophage cell line and is efficacious in increasing bacterial clearance in a mouse model of pneumonia." (PMID 34271850, 2021). "Treatment with partially desulfated heparin in preclinical models of pneumonia reduced airway HMGB1 levels and neutrophilic lung injury." (PMID 32380958, 2020). "Five diagnostic biomarkers have been linked to the diagnosis of pneumonia, namely: C-reactive protein (CRP), Procalcitonin (PCT), a Soluble triggering receptor expressed on myeloid cells-1 (STREM-1), CD163, and High Mobility Group Box-1(HMGB-1)." (PMID 33218302, 2020). "Treatment with anti-HMGB1 mAb provided partial protection against both pneumonia and encephalopathy in murine models of influenza infections despite that the treatments did not affect virus propagation in the lungs." (PMID 32380958, 2020). "The NLRP3-mediated control of K. pneumoniae-induced pneumonia involves the increased neutrophil infiltration, macrophage necrosis, and the release of high-mobility group box-1 protein (HMGB-1)." (PMID 32849610, 2020). "Accordingly, in experimental models the use of neutralizing anti-HMGB1 monoclonal antibody confers protection against lung injury and pneumonia, including pneumonia from influenza virus." (PMID 32760352, 2020). "In previous studies, our group successfully established a HAdV-7 pneumonia model in the laboratory mouse, and studies in this in vivo model suggested that HMGB1 is a mediator of HAdV-7-induced pulmonary inflammation." (PMID 30626350, 2019).
pneumonia (continued). "Relative to t = 0 h, mice with pneumonia induced by K. pneumoniae had elevated HMGB1 levels in BALF at 6, 24 and 48 h." (PMID 26824892, 2016). "In this study, we evaluated the therapeutic effects of anti-HMGB1 mAb on severe H1N1-induced pneumonia in mice." (PMID 26067826, 2015). "In comparison with control mice, animals that received recombinant HMGB1 showed fivefold higher bacilli loads, the double of pneumonia and significant lower expression of IFNγ, TNFα and IL-17, while the expression of IL-10 was significantly higher." (PMID 26201072, 2015). "This study was undertaken to evaluate the therapeutic effects of anti-high mobility group box-1 (HMGB1) monoclonal antibody (mAb) treatment on influenza A virus (H1N1)-induced pneumonia in mice." (PMID 26067826, 2015). "Intravenous administration of anti-HMGB1 mAb significantly improved the survival rate and attenuated lung histopathological changes in a murine model of influenza-induced pneumonia." (PMID 26067826, 2015). "During late disease, on day 28 and 60 of infection, there are extensive areas of pneumonia, the bronchial epithelium in these zones showed an accentuated decrease of HMGB1 immunostaining and macrophages were the most common and intense immunoreactive cells." (PMID 26201072, 2015). "Similar granuloma size was measured in both groups, but animals that received HMGB1 developed significant more pneumonia on day 28 of infection." (PMID 26201072, 2015). "Our results suggest a harmful role for both HMGB1 and RAGE in the development of lung injury during the early phase of severe pneumonia caused by a clinical relevant Gram-positive pathogen." (PMID 24342460, 2013). "For this we administered a monoclonal anti-HMGB1 antibody previously shown to inhibit HMGB1-induced acute and chronic inflammation in mice, including pneumonia." (PMID 24342460, 2013). "In addition, previous clinical studies have shown the clinical significance and prognostic role of HMGB1 in pneumonia, cholecystitis and pancreatitis." (PMID 37964313, 2023). "Furthermore, CA activates SIRT1 to inhibit nuclear translocation of HMGB1 and M2 polarization, thereby alleviating Klebsiella pneumoniae-induced pneumonia in AMs." (PMID 35873636, 2022). "Furthermore, HMGB1 was significantly increased in the serum of children with severe pneumonia who were infected with H1N1 influenza virus and was significantly associated with the upregulation of 10 other cytokines." (PMID 33140586, 2021). "Most of the evidence comes from experimental influenza virus models and acute lung injury where infection/injury induces increased HMGB1 levels in the lungs that contribute to the severity of pneumonia, correlate to death and can be blocked with HMGB1-specific antibody." (PMID 32670297, 2020). "The results demonstrated that systemic suppression of HMGB1 to its normal basal level by anti-HMGB1 mAb could protect against severe H1N1-induced pneumonia with almost complete survival." (PMID 26067826, 2015). "Further research on the downstream signaling pathways of the HMGB1-RAGE axis in influenza-induced pneumonia is warranted to clarify these speculations." (PMID 26067826, 2015). "It is reasonable to anticipate that high HMGB1 concentration may correlate with severity and mortality in relatively healthy patients who have severe pneumonia and ARDS." (PMID 24723739, 2014). "Therefore, treatment with anti-HMGB1 mAb itself could restrict RAGE expression in H1N1-induced pneumonia by blocking HMGB1-induced signaling, resulting in suppression of the inflammatory response." (PMID 26067826, 2015). "Silencing SIRT1 or overexpressing HMGB1 reversed these effects, confirming the role of the SIRT1–HMGB1 axis in CGA-mediated macrophage modulation and pneumonia resolution." (PMID 41465487, 2025). "Second, curcumin protects from lethal pneumonia and ARDS via targeting NF-κB, inflammasomes, IL-6 trans-signal, and high-mobility group box 1 (HMGB1) pathways." (PMID 35496320, 2022).
pneumonia (continued). "Thus, in a pneumonia lung, high levels of airway HMGB1 may impair bacterial killing." (PMID 30194360, 2018). "We provide evidence that large volume resuscitation with stored blood, compared to fresh blood, in mice increases mortality from subsequent pneumonia, which occurs via mechanisms sensitive to hemopexin and TLR4 and HMGB1 inhibition." (PMID 29522519, 2018). "Taken together, HMGB1‐RAGE axis plays important role in pneumonia and is a promising target for the treatment of pneumonia." (PMID 28039939, 2017). "HMGB1 contributes to the pathogenesis of influenza virus (H5N1) infection in mice by inducing extensive inflammatory responses and severe pneumonia." (PMID 27634894, 2016). "In a mouse model of HAdV-B7 pneumonia, in which infection leads to cell death but the virus does not replicate, application of a neutralizing antibody to HMGB1 reduced pulmonary inflammation." (PMID 40367285, 2025). "The results showed that the expression levels of IL-6, IFN-γ, IFN-α1, IP10, IL-10, HMGB1, and the HMGB1/sRAGE ratio were comparable between patients with or without pneumonia." (PMID 35875560, 2022). "Research studies in the pediatric population show that many inflammatory diseases, including respiratory system-related diseases like pneumonia/bronchiolitis, influenza virus or respiratory syncytial virus (RSV)-induced infection, and lung injury, correlate with increased levels of HMGB1." (PMID 35633962, 2022). "However, regulatory T cells (Tregs), cytokines (TGF-β1 and TNF-α), and DAMPs (HMGB1) do not play a significant role in the induction of paralyzed AMs during resolution of pulmonary inflammation following pneumonia." (PMID 32849610, 2020). "In comparison with the control group, animals that received blocking HMGB1 antibodies after 60 days of infection showed a significant increase of pulmonary bacilli burdens, lower expression of IFNγ, TNFα and IL17, high expression of IL-10, and higher but not significant pneumonia (39+/3% vs 32+/3%)." (PMID 26201072, 2015).
type 2 diabetes (43 papers, 2012 to 2026). "In a study on the involvement of HMGB1 in mechanical allodynia in a model of type 2 diabetes, the development of mechanical allodynia in the rodent was associated with upregulation of HMGB1 protein in the spinal cord." (PMID 27294160, 2016). "Our results are consistent with previous reports that demonstrated elevated levels of HMGB1 in the serum from patients with type 1 and type 2 diabetes and that higher serum HMGB1 levels were associated with greater prevalence and severity of albuminuria." (PMID 23766563, 2013). "In db/db mice, a model of type 2 diabetes, the development of mechanical allodynia is associated with the upregulation of HMGB1 protein in the spinal cord, and intrathecal injection of the neutralizing antibody against HMGB1 inhibited mechanical allodynia." (PMID 27216039, 2016). "The High Mobility Group Box 1 (HMGB1)/TLR4 axis is activated in type 2 diabetic (T2DM) neural tissues, and its inhibition by glycyrrhizin (GLC) improves nociceptive thresholds." (PMID 41574659, 2026). "HMGB1 is a key factor in the regulation of neuroinflammation and hippocampal neuronal apoptosis in type 2 diabetic mice exposed to intermittent hypoxia." (PMID 35578754, 2022). "Recently, the HMGB1/TLR4 expression levels were reported to be up regulated in spinal neurons of type 2 diabetic rodents with painful neuropathy along with marked mechanical and thermal hyperalgesia." (PMID 33915770, 2021). "RAGE is one of the receptors for HMGB1, and its expression is higher in gingival tissue of patients with type 2 diabetes than in healthy patients." (PMID 32760399, 2020). "Metformin, the first-line medication for the treatment of type 2 diabetes, is also considered an HMGB1 inhibitor because it directly binds HMGB1 and inhibits the pro-inflammatory activity." (PMID 32760399, 2020). "They surmised that HMGB-1-RAGE interaction contributed to islet cell apoptosis in type 2 diabetes by inducing oxidative stress." (PMID 27847406, 2016). "TLR2 also recognizes some DAMPs as endogenous ligands, including human glycosaminoglycan hyaluronan, β-defensin-3, heat shock proteins and high mobility group box 1 protein, some of which are released during inflammatory diseases like type 2 diabetes." (PMID 28536605, 2016). "HMGB1 was also thought to be involved in the pathogenesis of type 2 diabetes (T2D)." (PMID 30410469, 2018). "Circulating CTRP-3 and HMGB-1 concentrations might be promising biomarkers to predict prediabetes and type 2 diabetes." (PMID 27738641, 2016). "In addition, HMGB1 and RAGE interaction induced islet cells apoptosis and progressive β-cell loss by inducing oxidative stress in type 2 diabetic rats." (PMID 28101517, 2016). "Hence, HMGB1 plays an important role in the painful neuropathy of Type 2 diabetic animals and it might exhibit a unique target for the treatment of this debilitating condition." (PMID 32019145, 2020). "Because others have suggested that danger associated molecular patterns (DAMPs) can activate inflammasomes in type 2 diabetes, we wanted to investigate whether the cytosolic HMGB1 could stimulate formation of the NLRP3 inflammasome in the retina, as well as the role of Epac1 in this activation." (PMID 28348460, 2017).
type 2 diabetes (continued). "HMGB1 and RAGE levels are elevated in db/db type 2 diabetic mouse model and high glucose‐treated NCM460 colon cells, while butyrate suppresses the abnormal proliferation of colonic epithelial cells under diabetic state by targeting HMGB1‐RAGE." (PMID 35706377, 2022). "The results from this study suggest that the elevation of inflammatory mediators, including HMGB1 in DRG and spinal cord, are important in the development of painful neuropathy in Type 2 diabetes along with changes in histone acetylation." (PMID 32019145, 2020). "HMGB-1 signaling pathway components including receptors for HMGB-1 and NF-κB were significantly upregulated in type 2 diabetic retinas and in high-glucose-treated retinal cells (acute retinal pigment epithelitis-19 cells (ARPE-19 cells) and RGC-5 cells)." (PMID 27847406, 2016). "The discovery that RAGE interacts with non-AGE ligands, such as S100/calgranulins and high mobility group box 1 (HMGB1), suggests that RAGE is not only involved in diabetic complications but also contributes to the development of both type 1 and type 2 diabetes." (PMID 38003949, 2023). "Moreover, the interaction among HMGB1, RAGE and TLR further exacerbates inflammation and increases the development of complications in patients with type 2 diabetes." (PMID 33114431, 2020). "Interestingly, another study showed that not only TLR2 has been more highly expressed on the immune cells of type 2 diabetes patients than on those of healthy subjects, but also the levels of TLR2 ligands, including hyaluronan, HSP60, HSP70, HMGB1 and endotoxin, were higher." (PMID 28536605, 2016). "In this retrospective observational study, we have analyzed HMGB-1, OPG and inflammatory cytokines serum levels in 1393 type 2 diabetic patients with PAD and without PAD (WPAD)." (PMID 28789654, 2017).
bladder cancer (42 papers, 2013 to 2026). "HMGB1 is upregulated in bladder cancer and is closely associated with the tumor grade and tumor stage." (PMID 31848324, 2019). "Most importantly, the elevation of HMGB1 activates the autophagy pathway and has been implicated in the development of radioresistance in bladder cancer." (PMID 28642840, 2017). "In this study, we found that HMGB1 expression was significantly increased in bladder cancer tissues, which was associated tumor grade and T stage." (PMID 29069735, 2017). "In addition, the expression level of HMGB1 is closely related to the pathological grading and prognosis of bladder cancer, which makes it a potential diagnostic and prognostic biomarker." (PMID 40969278, 2025). "Notably, GDF15 and HSP90 correlate with ferroptosis susceptibility in RCC and urinary VEGF with HMGB1 increases the chances of non-invasive bladder cancer detection." (PMID 41009692, 2025). "From a diagnostic perspective, the study reported a urinary HMGB1 cut-off value of 63.3 pg/mL to differentiate bladder cancer from urinary tract infections, with a specificity of 77% and sensitivity of 59%, and an AUC of 0.813 against healthy controls—supporting its clinical potential." (PMID 41009692, 2025). "For bladder cancer, urinary HMGB1 plus VEGF appears particularly attractive, since they capture complementary processes and both are measurable in urine." (PMID 41009692, 2025). "In the context of bladder cancer, elevated HMGB1 expression also correlates with advanced tumor stages and poor patient outcomes." (PMID 41009692, 2025). "Given these multifaceted roles, HMGB1 emerges as a biomarker and a therapeutic target in bladder cancer." (PMID 41009692, 2025). "Glutathione S-transferase zeta 1 (GSTZ1) enhances ferroptosis through the HMGB1/GPX4 pathway in bladder cancer cells, indicating that HMGB1 promotes ferroptosis via inhibiting the pathways related to antioxidant defenses." (PMID 39994144, 2025). "The comprehensive insights provided by this study advocate for further investigation into HMGB1-targeted therapies in bladder cancer management." (PMID 41009692, 2025). "Meanwhile, IGF2BP3 enhanced the stability of oncogene HMGB1 by binding to its mRNA and promoted the expression of HMGB1 in bladder cancer." (PMID 40083693, 2025). "In prostate and bladder cancers, HMGB1 released during chemotherapy boosts autophagy via Beclin-1, reducing drug toxicity and aiding tumor survival." (PMID 40969278, 2025). "Further large-scale and longitudinal studies are warranted to validate these findings and explore HMGB1 as a biomarker-integrated target in bladder cancer management." (PMID 41009692, 2025). "HMGB1 exhibits tumor-promoting effects in a wide range of cancers, and its specific mechanisms are gradually being revealed in bladder cancer." (PMID 40969278, 2025). "Significantly elevated urinary HMGB1 levels were observed in patients with bladder cancer compared to both healthy controls and those with urinary tract infections, indicating HMGB1’s potential as a discriminative marker." (PMID 41009692, 2025). "HMGB1 enhances chemotherapeutic drug resistance in bladder cancer cells by promoting their proliferation and migration and inhibiting their apoptosis." (PMID 41354099, 2025). "Knockdown of HMGB1 strongly enhances gemcitabine-induced apoptosis in bladder cancer cells and suppresses autophagy." (PMID 38725632, 2024). "Analysis of TCGA BLCA dataset revealed that mRNA levels of HMGB1 were elevated in bladder cancer samples as compared to normal tissues." (PMID 38504159, 2024). "The present research revealed that expression of IGF2BP3, acting as a positive regulator of HMGB1, exhibited a positive correlation with the degree of immune cell infiltration in bladder cancer." (PMID 38504159, 2024).